CPNE3 (copine 3)
Diseases named in the same sentence as CPNE3 in open-access papers:
CPNE3 is named in the same sentence as 33 diseases in open-access papers, as found by Europe PMC text mining. Sharing a sentence is not in itself a finding about the gene and the disease. The quoted sentences say what the papers report.
breast carcinoma (6 papers, 2004 to 2025). "Other studies suggest that binding of CPNE3 to ERBB2 is increased when Jab1 is overexpression in SKBR3 breast cancer cells." (PMID 35003348, 2021). "CPNE3 is a functional protein in many diseases, especially in cancers, such as non-small cell lung cancer, breast cancer, prostate cancer, colorectal cancer and acute myocardial infarction 9-13." (PMID 35003348, 2021). "Copine 3 is found as a novel player in the regulation of ErbB2-dependent cancer cell motility in breast cancer T47D cells." (PMID 31487856, 2019). "Human copine 3 was shown to translocate from the cytosol to the plasma membrane in response to a rise in calcium concentration and colocalize with activated ErbB2 receptors in breast cancer cells." (PMID 31330887, 2019). "It has been reported that CPNE3 can induce epithelial–mesenchymal transition (EMT) in breast cancer by activating ErbB2 protein and then can promote the invasion and migration of breast cancer cells." (PMID 41190648, 2025).
colorectal cancer (5 papers, 2021 to 2025). A primary or metastatic malignant neoplasm that affects the colon or rectum. "Colorectal cancer patients with lower levels of exosomal CPNE3 have better disease-free survival and overall survival (OS), suggesting that CPNE3 can serve as a diagnostic and prognostic biomarker." (PMID 38493426, 2024). "Another report identified Copine 3 or CPNE3 as elevated in exosomes isolated from the plasma of colorectal cancer patients compared to healthy control." (PMID 39001524, 2024). "Colorectal cancer patients with lower exosomal CPNE3 levels had substantially better disease-free survival and overall survival, implying that CPNE3 is a diagnostic and prognostic biomarker." (PMID 34367247, 2021). "In colorectal cancer, relevant studies have found that patients with low CPNE3 levels in exosomes have significantly better disease‐free survival and overall survival, suggesting that CPNE3 may be used as a biomarker to diagnose and evaluate the prognosis of colorectal cancer." (PMID 41190648, 2025).
prostate carcinoma (5 papers, 2017 to 2023). A carcinoma that arises from epithelial cells of the prostate gland. "The higher expression of CPNE3 has been observed in several cancers, however, the decrease in its expression level was also observed in prostate cancer." (PMID 33630973, 2021). "CPNE3 could promote cell motility by interacting with epithelial membrane protein 1 in prostate cancer cells." (PMID 37469397, 2023). "It was demonstrated using luciferase assays that miR133-b represses CPNE3 in prostate cancer." (PMID 28035070, 2017).
Anxiety (4 papers, 2021 to 2025). Intense feelings of nervousness, tension, or panic often arise in response to interpersonal stresses. "Notably, CPNE3 is highly expressed in Schwann cells and has been linked to dysregulation in patients with schizophrenia, Alzheimer’s disease, and individuals exhibiting heightened anxiety and reduced working memory." (PMID 41342963, 2025). "The current study found that CPNE3 interacted with anxiety to affect working memory, and replicated the finding in an independent sample." (PMID 33767297, 2021). "This interaction effect was replicated in the replication sample by MAGMA gene analysis (p = 0.039 for CPNE3) as well as the gene-score-by-anxiety interaction analysis (p = 0.0016)." (PMID 33767297, 2021). "In summary, the current study searched the whole genome and found that CPNE3 interacted with anxiety to affect WM, with rs10102229 showing the strongest effect." (PMID 33767297, 2021). "A recent study reported that CPNE3 interacts with anxiety to affect working memory (WM)." (PMID 37095366, 2023). "According to BrainSeq and GTEx, the TT genotype of rs10102229 was associated with a lower expression of CPNE3, and we found that WM and anxiety showed a negative correlation in this group (i.e., higher anxiety was linked with worse WM), which was similar to the pattern of schizophrenia patients." (PMID 33767297, 2021). "We would like to point out that neither the correlation between anxiety and WM nor the main effect of CPNE3 on WM was significant, suggesting the true action was the interaction between anxiety and CPNE3, which had not been tested before." (PMID 33767297, 2021).
diabetes (3 papers, 2020 to 2025). "Another integration-driven discovery, CPNE3, which encodes a calcium-dependent membrane-binding protein, has also been described in patients with diabetes." (PMID 41465472, 2025). "This study is the first to link CPNE3 with the pathophysiology of diabetes to the best of our knowledge." (PMID 34667273, 2021). "However, comparable levels of PECAM1, CXCR2, SLC2A3, BST2, S100A11, S100A12, and CPNE3 were found in neutrophils from diabetes patients and controls (P > 0.05)." (PMID 32377527, 2020).
glioblastoma (3 papers, 2021 to 2025). The most malignant astrocytic tumor (WHO grade IV). "In glioblastoma, studies have shown that CPNE3 can promote the proliferation, migration and invasion of tumour cells by activating the PI3K/AKT pathway." (PMID 41190648, 2025). "For example, in glioblastoma, a study found that the high expression of CPNE3 can inhibit the invasion, migration and proliferation of glioblastoma cells by inactivating the FAK signalling pathway." (PMID 41190648, 2025). "The specific role of CPNE3 in glioblastoma is still controversial." (PMID 41190648, 2025). "Previous studies have demonstrated that CPNE3 triggers the PI3K/AKT signaling pathway to regulate the proliferation and apoptosis of human glioblastoma cells." (PMID 39524444, 2024).
lung carcinoma (3 papers, 2016 to 2025). "The expression of CPNE3 in normal tissues and lung cancer tissues was compared using a public database." (PMID 41190648, 2025). "We first investigated the possible role of CPNE3 in non‐small cell lung cancer through numerous bioanalysis sites." (PMID 41190648, 2025). "We found that CPNE3 expression is elevated in non‐small cell lung cancer and is predicted to function as an oncogene, which is significantly correlated with TNM staging and poor prognosis in patients." (PMID 41190648, 2025). "Previously, it has been reported that CPNE3 may be an important gene involved in the metastasis of non‐small cell lung cancer and has the potential to become a novel therapeutic target." (PMID 41190648, 2025). "With the support of the data, we believe that CPNE3 plays a cancer‐promoting role in non‐small cell lung cancer and may be a new therapeutic target or an independent prognostic factor for patients." (PMID 41190648, 2025). "To further determine the relationship between CPNE3 and RACK1, we collected 12 pairs of NSCLC lung cancer tissue and corresponding adjacent tissue samples." (PMID 41190648, 2025). "As an example, myosin heavy chain 9 (MYH9) and Copine III (CPNE3) positively correlate with the migration and invasion properties of lung cancer cell lines." (PMID 27018053, 2016).
non-small cell lung carcinoma (3 papers, 2004 to 2021). A group of at least three distinct histological types of lung cancer, including non-small cell squamous cell carcinoma, adenocarcinoma, and large cell carcinoma. "CPNE3 promotes migration and invasion in non-small cell lung cancer by interacting with RACK1 via FAK signaling activation." (PMID 34367247, 2021). "CPNE3 can promote migration and invasion in non-small cell lung cancer by interacting with RACK1 via FAK signaling activation." (PMID 34367247, 2021).
breast tumors (2 papers, 2021). "In primary breast tumors, high CPNE3 RNA levers significantly correlate with ERBB2 amplification." (PMID 35003348, 2021).
glioma (2 papers, 2021 to 2022). A benign or malignant brain and spinal cord tumor that arises from glial cells (astrocytes, oligodendrocytes, ependymal cells). "In order to select proper cell model, we then analyzed the expression of CPNE3 in human glioma cell lines, A172, T98G, U251 and U87, as well as human glial cell line HEB." (PMID 35003348, 2021). "Our data provided evidence suggesting that CPNE3 may affect glioma cell proliferation and apoptosis by activating the PI3K/AKT signaling pathway." (PMID 35003348, 2021). "All the glioma cell line featured with a significantly higher CPNE3 mRNA and protein expression when compared with HEB cell line, and the glioma cell lines with the highest (U251) and the lowest (T98G) expression were selected for the CPNE3 knock-down and overexpression study." (PMID 35003348, 2021).
lymph node metastasis (2 papers, 2024 to 2025). "CPNE3 expression is significantly associated with tumour stage, lymph node metastasis and distant metastasis in LUAD." (PMID 41190648, 2025). "The depth of local infiltration, lymph node metastasis, TNM stage, and high CPNE3 expression were prognostic variables in GC according to the findings of univariate Cox regression analysis." (PMID 38493426, 2024).
type 2 diabetes (2 papers, 2020 to 2021). "Taken together, data from the present study provides a new understanding of the role of CPNE3 in maintaining normal β-cell function, which might contribute to developing a novel target for future management of type 2 diabetes therapy." (PMID 34667273, 2021).
endometriosis (1 paper, 2025). The growth of functional endometrial tissue in anatomic sites outside the uterine body. "Another study found that BANCR expression increased gradually during the malignant transformation of endometriosis, and the expression levels of CPNE3 were remarkably upregulated, while those of miR-612 were downregulated (p < 0.05)." (PMID 40364006, 2025).
hepatocellular carcinoma (1 paper, 2025). A malignant tumor that arises from hepatocytes. "In hepatocellular carcinoma, studies have confirmed that knockdown of CPNE3 expression can enhance the sensitivity of hepatocellular carcinoma cells to the molecularly targeted drug sorafenib." (PMID 41190648, 2025).
insulinoma (1 paper, 2025). "A study conducted in 2021 demonstrated that silencing of Cpne3 in a rat insulinoma cell line suppresses glucose-stimulated insulin secretion." (PMID 41465472, 2025).
lung adenocarcinoma (1 paper, 2025). A carcinoma that arises from the lung and is characterized by the presence of malignant glandular epithelial cells. "Moreover, we examined the expression of CPNE3 in 45 pairs of lung adenocarcinoma (LUAD) tissues and matched adjacent non‐tumour tissues using tissue microarray technology." (PMID 41190648, 2025).
Stroke (1 paper, 2025). Sudden impairment of blood flow to a part of the brain due to occlusion or rupture of an artery to the brain. "Another protein implicated in stroke recovery is copine-3 (Cpne3), which was upregulated in the chronic phase and may be associated with late-stage recovery processes." (PMID 41342963, 2025).
triple-negative breast carcinoma (1 paper, 2024). An invasive breast carcinoma which is negative for expression of estrogen receptor (ER), progesterone receptor (PR), and human epidermal growth factor receptor 2 (HER2). "According to the qRT−PCR results, the mRNA expression of MTMR9 and CPNE3 was greater in triple-negative breast cancer (TNBC) cell lines (MDA-MB-231 and BT549) and ER-, PR-, and HER2+ BRCA cell line (SUM149PT)." (PMID 39524444, 2024).
cancer (12 papers, 2018 to 2025). A tumor composed of atypical neoplastic, often pleomorphic cells that invade other tissues. "Furthermore, CPNE3 expression increased with cancer progression, and CPNE3 enhanced the diagnostic power of carcinoembryonic antigen (CEA), a previously identified biomarker, when used in conjunction." (PMID 39001524, 2024). "Although the expression of CPNE3 was associated with cancer pathogenesis and metastasis, this could indicate that CPNE3 has a differential physiological function/role that depends on the cell or microenvironment." (PMID 34667273, 2021). "As an important member of this family, CPNE3 also plays an important role in the occurrence and progression of cancer." (PMID 41190648, 2025). "The role of CPNE3 in various cancers has been confirmed, but the specific molecular mechanism of CPNE3 in NSCLC remains to be further investigated." (PMID 41190648, 2025). "Copine 3 (CPNE3) is a calcium-dependent phospholipid-binding protein that has been found to play an essential role in cancer progression and stages." (PMID 34667273, 2021). "We wanted to determine how CPNE3 plays a significant role in promoting cancer." (PMID 41190648, 2025). "The PI3K/AKT pathway plays an essential role in cell proliferation in various types of cancer, which implied that CPNE3 may modulate the proliferation and apoptosis of GBM by affecting PI3K/AKT pathway." (PMID 35003348, 2021). "A total of 10 pairs with high expression of CPNE3 and 11 pairs with high expression of RACK1 were found in cancer tissue." (PMID 41190648, 2025). "To explore the role of CPNE3 in GC, we analyzed the mRNA expression levels using the GEPIA database and found that CPNE3 mRNA was highly expressed in multiple cancers." (PMID 38493426, 2024). "SCIN, LRP1B, CPNE3, TICRR, and PPP1R7 are connected to cancer cell invasion, migration, proliferation, and apoptosis." (PMID 37628788, 2023). "We collected 30 pairs of fresh cancer tissues and adjacent tissues from patients with NSCLC after surgery, and we extracted RNA from the tissues and performed qRT–PCR to detect the mRNA expression of CPNE3." (PMID 41190648, 2025). "Among these, CPNE3 (copine-3) was demonstrated to interact with ERBB2 through a receptor dependent manner and it may be a novel factor regulating the ERBB2-dependent cancer cell motility." (PMID 35685794, 2022).
tumor (8 papers, 2021 to 2026). "For example, the effects of different mutation types on MTMR9 and CPNE3 expression levels can be analyzed to understand how these mutations drive disease progression in the tumor microenvironment." (PMID 39524444, 2024). "Western blotting showed that the levels of CPNE3, p‐AKT and p‐ERK in CPNE3‐overexpressed tumours were significantly increased compared with control cells." (PMID 41190648, 2025). "To further analyze the changes in CPNE3 expression during tumor progression, we performed a pseudotime series analysis of epithelial cells." (PMID 39524444, 2024). "CPNE3 knockdown dramatically slowed tumor development in vivo, and the tumor weight of CDX (n = 10/group) models was significantly suppressed (mean ± standard error of the mean: sgRNA-CPNE3 vs. sgRNA-NC: 0.257 ± 0.028 vs. 0.716 ± 0.063; p < 0.01)." (PMID 38493426, 2024). "The fluorescence signal of PCNA and Ki67 were significantly decreased in tumor tissues from CPNE3 knock-down group." (PMID 35003348, 2021). "We found that, in addition to interacting with CD2, CD58 was co-expressed and physically interacted with HOXB family genes (HOXB2, HOXB3, and HOXB5), AKAP12, CLIC1, CPNE3, etc., which were reported to be involved in tumor initiation and progression." (PMID 34193136, 2021). "In addition, CPNE3 expression is significantly elevated across tumour stages (I–IV) compared with normal tissues (Kruskal–Wallis test, p = 1.15e−10)." (PMID 41190648, 2025). "We further tested the regulatory effect of CPNE3 overexpression on tumour growth in vivo." (PMID 41190648, 2025). "The results suggested that the c‐MET inhibitor JNJ‐38877605 could significantly inhibit the growth of transplanted tumours with CPNE3‐overexpressing cells in nude mice." (PMID 41190648, 2025). "Collectively, these findings imply that high CPNE3 expression facilitates GC tumor growth in vivo." (PMID 38493426, 2024). "In addition, recent studies have also found that CPNE3 is highly expressed in breast cancer, prostate cancer and ovarian cancer and is involved in tumor cell proliferation and metastasis." (PMID 34367247, 2021). "Cpne3 along with Rac1 is required for cell migration during tumor metastasis." (PMID 34847148, 2021). "Mechanistically, CPNE3 exhibits kinase activity, phosphorylates Hl histones and basic phospholipid proteins, activates downstream signaling pathways, and subsequently promotes tumor proliferation and metastasis." (PMID 34367247, 2021). "Further clustering of the tumor cells identified six cell subpopulations, among which multiple Copines genes, especially CPNE1 and CPNE3, showed a high expression." (PMID 40337972, 2026). "However, the internal mechanism of CPNE3 in mediating tumour progression remains unclear." (PMID 41190648, 2025). "We used Crisp-Cas9 gene editing to construct a BGC-823 cell line with a stable knockdown of CPNE3, CDX, and PDX, which showed that targeting CPNE3 significantly inhibited tumor growth." (PMID 38493426, 2024). "The expression levels of CPNE3, YAP1, and CYR61 were remarkably reduced in the tumor tissues of the CPNE3-silenced group." (PMID 38493426, 2024). "To further study the biological function of CPNE3 in vivo, we established CDX tumor models using Clustered Regularly Interspaced Short Palindromic Repeats (CRISPR)-associated protein 9 (CRISPR/Cas9)." (PMID 38493426, 2024). "Tumor tissues from the PDX models were analyzed by WB and IHC, and the results indicated that YAP1 and CYR61 protein levels significantly decreased when CPNE3 was downregulated." (PMID 38493426, 2024). "The expression of CPNE3, YAP1, CYR61, and RAD51 proteins in tumor tissue samples from 100 randomly selected patients with GC was examined using continuous-section IHC labeling." (PMID 38493426, 2024). "Heinrich C found that CPNE3 induces EMT by activating the ErbB2 protein and induces tumor cell invasion and migration." (PMID 34367247, 2021).
tumor (continued). "To investigate the function of CPNE3 in GBM, we first compared the expression of CPNE3 in GBM tumor tissues and adjacent normal tissues from TCGA/GEPIA dataset." (PMID 35003348, 2021). "CPNE3 is highly expressed in NSCLC and can promote the proliferation and migration of tumour cells." (PMID 41190648, 2025). "The A549 cells stably overexpressing CPNE3 were used to inoculate athymic BALB/C nude mice, and the tumours formed with CPNE3‐overexpressed cells were significantly larger in tumour volume than those formed with control cells, and the growth rates were significantly faster." (PMID 41190648, 2025). "We performed IHC to analyze CPNE3 protein expression in tumor tissues (n = 20) and paired normal tissues (n = 20) from patients with GC." (PMID 38493426, 2024). "IHC demonstrated the upregulation of ACSF2, MTMR9, and CPNE3 in BRCA tissues, whereas ACSL1 expression was not significantly different between tumor tissues and adjacent tissues." (PMID 39524444, 2024). "IHC of continuous sections obtained from the same patient's cancerous and non-cancerous tissues revealed that CPNE3, YAP1, CYR61, and RAD51 were significantly positive in the tumor tissue and negative in the non-cancerous tissue." (PMID 38493426, 2024).
CPNE3 also shares sentences with these, for which no sentence is quoted: acute myocardial infarction (2 papers); metastatic prostate carcinoma (2); schizophrenia (2); acute myeloid leukemia (1); Alzheimer disease (1); colon cancer (1); COVID-19 (1); gastric cancer (1); infection (1); neurological disorders (1); ovarian endometrioid adenocarcinoma (1); ovarian endometrioid carcinoma (1); periodontitis (1).